AOC2 (amine oxidase copper containing 2)
Description:
Catalyzes the oxidative deamination of primary amines to the corresponding aldehydes with the concomitant production of hydrogen peroxide and ammonia. Has a preference for 2-phenylethylamine, tryptamine and tyramine. Could also act on methylamine and benzylamine but much less efficiently.
Synonyms: RAO; SSAO; DAO2
Tractability: Small molecule: it belongs to a druggable protein family. Antibody: UniProt places it where antibodies can reach, with high confidence; its Gene Ontology location is reachable by antibodies, with high confidence; UniProt predicts a signal peptide or a membrane-spanning region. PROTAC: a small molecule that binds it is known.
Target class: Enzyme; Oxidoreductase
Gene: Protein-coding gene on chromosome 17 (42,844,580 to 42,850,707, forward strand). Ensembl gene ENSG00000131480.
Subcellular location: Cell membrane (Isoform 1); Cytoplasm (Isoform 2)
Pathways (Reactome):
Metabolism: Phase I - Functionalization of compounds
Gene Ontology:
Molecular function: protein binding; copper ion binding; electron transfer activity; primary methylamine oxidase activity; quinone binding
Biological process: amine metabolic process; visual perception; xenobiotic metabolic process
Cellular component: cytoplasm; plasma membrane
Genetic constraint (gnomAD): Loss-of-function variants: 62 observed, 59.28 expected, observed/expected ratio (o/e) 1.05, 90% interval 0.85 to 1.29. The upper end of that interval is the gene's LOEUF score, 1.29, which puts it in group 5 of 6, group 1 being the genes least tolerant of losing a copy. Missense variants: 1,008 observed, 1,000.1 expected, observed/expected ratio (o/e) 1.01, 90% interval 0.96 to 1.06. Synonymous variants: 404 observed, 417.99 expected, observed/expected ratio (o/e) 0.97, 90% interval 0.89 to 1.05.
Homologues: Orthologues: chimpanzee AOC2 (99% identical), macaque AOC2 (99% identical), dog AOC2 (89% identical), pig AOC2 (88% identical), rabbit AOC2 (87% identical), mouse Aoc2 (81% identical), zebrafish aoc2 (42% identical). Paralogues in human: AOC3 (66% identical), AOC1 (40% identical).
Diseases named in the same sentence as AOC2 in open-access papers:
AOC2 is named in the same sentence as 16 diseases in open-access papers, as found by Europe PMC text mining. Sharing a sentence is not in itself a finding about the gene and the disease. The quoted sentences say what the papers report.
retinal diseases (2 papers, 2022 to 2025). "AOC2 gene encodes retinal-specific amine oxidase, and human AOC2 is thought to play a role in hereditary retinal diseases." (PMID 40343124, 2025). "Its physiological role is still unclear, but a previous study suggested that AOC2 plays a role in hereditary retinal diseases." (PMID 35281080, 2022).
amyotrophic lateral sclerosis (1 paper, 2023). Amyotrophic lateral sclerosis (ALS) is a neurodegenerative disease characterized by progressive muscular paralysis reflecting degeneration of motor neurons in the primary motor cortex, corticospinal tracts, brainstem and spinal cord. "AOC2 is involved in oxidation by cytochrome P450 and meta-pathway biotransformation phases I and II, which are associated with median neuropathy and amyotrophic lateral sclerosis." (PMID 37761835, 2023).
bladder cancer (1 paper, 2025). "In the present study, we constructed a novel and highly reliable four-gene marker (OAS1, AOC2, HOXB5, and HSH2D) for predicting the prognosis of bladder cancer based on TPECs-related genes." (PMID 41584451, 2025).
cataract (1 paper, 2019). Partial or complete opacity of the crystalline lens of one or both eyes that decreases visual acuity and eventually results in blindness. "Moreover, notably, harmaline or its derivatives have been detected in human tissues such as the eyes of cataract patients, where AOC2 is specifically expressed." (PMID 30679427, 2019).
diabetes (1 paper, 2014). "Ontological classification demonstrates that these 14 genes are associated with diabetes (ALMS1P; RAET1L; GYS1; RBM47; EFR3B), cancer (RPL27A; SPAM1; PTCH1; ZNF277; USP35; CDC86), or metabolism (C3orf15; AOC2; GOT1)." (PMID 24885560, 2014).
osteoarthritis (1 paper, 2024). A noninflammatory degenerative joint disease occurring chiefly in older persons, characterized by degeneration of the articular cartilage, hypertrophy of bone at the margins and changes in the synovial membrane. "For instance, curcumin may exhibit therapeutic effects on osteoarthritis by modulating the CBS, CTH, PSAT1, MAOA, and AOC2 proteins involved in the metabolism of glycine, serine, and threonine." (PMID 37938371, 2024).
Stroke (1 paper, 2023). Sudden impairment of blood flow to a part of the brain due to occlusion or rupture of an artery to the brain. "Based on the role of metabolism in stroke, we extracted seven genes related to the “porphyrin metabolism” and “glycine, serine and threonine metabolism” pathways, including ALAS2, FECH, COX10, GCAT, HMBS, PGAM2, and AOC2." (PMID 36968495, 2023).
triple-negative breast carcinoma (1 paper, 2025). An invasive breast carcinoma which is negative for expression of estrogen receptor (ER), progesterone receptor (PR), and human epidermal growth factor receptor 2 (HER2). "A Venn diagram further identified three potential key TRGs in triple-negative breast cancer (TNBC), namely ADH1A, AOC2, and TYRP1." (PMID 41006587, 2025).
cancer (2 papers, 2014 to 2024). A tumor composed of atypical neoplastic, often pleomorphic cells that invade other tissues. "For instance, the GAD2, AOC2 and DPYS had the hypermethylation in more than most of human cancers; on the contrary, most of βAMRGs showed the hypomethylation in more than most of human cancers." (PMID 38637116, 2024).
infection (2 papers, 2021 to 2023). The state of being infected such as from the introduction of a foreign agent such as serum, vaccine, antigenic substance or organism. "Most genes upstream of JA biosynthesis were highly induced after infection, particularly in Q24, such as the lipoxygenase gene (LOX, Csa7G449420, Csa4G286990), allene oxide synthase (AOS, Csa2G360780), and allene oxide cyclase 2 (AOC2, Csa5G366670)." (PMID 34194451, 2021).
tumor (2 papers, 2022 to 2024). "Of the 16 metabolism-related genes, we found that AOC2, IDUA, GPC2, CSPG4, TPST1, and CYP1B1 were differentially expressed between tumor and normal tissue at the protein level according to the Human Protein Atlas (HPA) cohort." (PMID 35281080, 2022). "Of the 16 metabolism-related genes, we found AOC2, IDUA, GPC2, CSPG4, TPST1, and CYP1B1 to be differentially expressed between tumor and normal tissues at the protein level." (PMID 35281080, 2022).
AOC2 also shares sentences with these, for which no sentence is quoted: breast carcinoma (1 paper); dwarfism (1); Huntington disease (1); Insulin resistance (1); Obesity (1).